IL33 (interleukin 33)
Diseases named in the same sentence as IL33 in open-access papers (continued):
Sharing a sentence is not in itself a finding about the gene and the disease.
colorectal cancer (58 papers, 2016 to 2025). A primary or metastatic malignant neoplasm that affects the colon or rectum. "The expression and interaction of interleukins IL-8, IL-17A, and IL-33 in colorectal cancer are closely associated with the degree of tumor invasion and play a pivotal role in disease progression." (PMID 40725273, 2025). "The expression of interleukins IL-8, IL-17A, and IL-33 in colorectal cancer demonstrates a strong association with the depth of tumor invasion across histological layers." (PMID 40725273, 2025). "The expression of interleukins IL-8, IL-17A, and IL-33 in colorectal cancer is significantly associated with the degree of tumor differentiation, and their interplay appears to influence tumor progression." (PMID 40725273, 2025). "Nevertheless, this soluble IL-33 receptor can also be associated with a good prognosis in colorectal cancer, as the trapping of soluble IL-33 in the TME inhibits cancer growth and metastases." (PMID 30416507, 2018). "This study demonstrated that the expression patterns of interleukins IL-8, IL-17A, and IL-33 are significantly associated with the histological grade and depth of tumor invasion in colorectal cancer, offering valuable insights into tumor aggressiveness and immune dynamics." (PMID 40725273, 2025). "In a colorectal cancer mouse model, IL-33 deficiency reduced mast cell accumulation in tumors." (PMID 30416507, 2018). "Increased expression of Interleukin (IL)-33 has been detected in intestinal samples of patients with ulcerative colitis, a condition associated with increased risk for colon cancer, but its role in the development of colorectal cancer has yet to be fully examined." (PMID 28710436, 2017). "We previously showed that Il1rl1 expression on macrophages is associated with low CD8+ T cell cytotoxicity and inhibition of the IL-33/Il1rl1 pathway with an IL-33trap enhances antigen-specific T cell responses in vivo in colorectal cancer models." (PMID 40659660, 2025). "Collectively, these results support the potential utility of IL-8, IL-17A, and IL-33 as biomarkers for assessing tumor behavior and as possible targets for personalized therapeutic interventions in colorectal cancer." (PMID 40725273, 2025). "The expression patterns of interleukins IL-8, IL-17A, and IL-33 in colorectal cancer vary according to tumor grade, playing a significant role in disease progression and prognosis." (PMID 40725273, 2025). "Interleukin-33 (IL-33) is a member of the IL-1 cytokine family that plays a dual role in colorectal cancer (CRC), acting as both a promoter and potential suppressor of tumor development depending on the context of the tumor microenvironment." (PMID 40725273, 2025). "Certainly, it is essential to dissect the precise and multifaceted mechanisms of IL33 downstream signaling within the colorectal cancer liver metastasis microenvironment." (PMID 41214328, 2025). "Collectively, these results emphasize the relevance of IL-8, IL-17A, and IL-33 in the mechanisms of tumor invasion and support their potential utility as biomarkers and therapeutic targets in colorectal cancer management." (PMID 40725273, 2025). "In mouse models, targeting IL33 blocked neutrophil lipid synthesis, decreased the colonization of colorectal cancer cells in the liver, and enhanced the efficacy of immunotherapy." (PMID 41214328, 2025). "The mode of action of IL-33/ST2 in solid tumors is predominantly driven by type-2 tumor-associated macrophages (TAM), as has been shown in colorectal cancers, squamous cell carcinoma, and ovarian cancers." (PMID 40691440, 2025). "In another study, anti-IL-33 antibody treatment reduced inflammation and improved the efficacy of chemotherapy in a colorectal cancer model." (PMID 38662248, 2024). "HIF-1α: hypoxia inducible factor-1 alpha, CRC: Colorectal cancer, IL-33: Interleukin-33, IQR: interquartile range, n: number, T: tumor size, N: nodes." (PMID 38313904, 2024).
colorectal cancer (continued). "It has been shown that IL33 can promote metastasis of colorectal cancer in mice by being activated by proinflammatory cytokines released in tumour microenvironments." (PMID 38398137, 2024). "In the context of cancer, IL-33-activated ILC2 cells were found to bear anti-tumoral functions in lung cancer while IL-25-activated ILC2 cells promoted tumorigenesis in colorectal cancer." (PMID 37781372, 2023). "Similar studies have depicted an increase in IL-33 in colorectal cancer compared to normal tissues, and its antitumorigenic effect in CRC." (PMID 37176567, 2023). "On the contrary, IL‐33 has anti‐tumourigenic role in hepatocellular carcinoma and colorectal cancer." (PMID 35344301, 2022). "In ovarian cancer, expression levels of both IL-33 and ST2 were negatively correlated with patient survival time, while lower serum sST2 was found to be linked to malignant growth of colorectal cancer." (PMID 35677533, 2022). "A recent study showed that IL-33 promotes function and accumulation of intratumoral Tregs to facilitate immunoevasion of colorectal cancer." (PMID 35720275, 2022). "IL-33-activated eosinophils in the TME were capable of restricting tumor growth in mouse models of colorectal cancer." (PMID 34209038, 2021). "A high level of IL-33 in cancer was observed in this study at approximately 53% in CCA tissues compared to 38% reported in colorectal cancer 24, 41% in hepatocellular carcinoma 25, 59% - 67% in ovarian cancer 26, 27 and 56% in non-small cell lung cancer." (PMID 33046978, 2020). "Although IL33 is elevated in colorectal cancer (CRC) patients when compared to normal tissues, in some studies its levels were reduced when comparing late vs. early stage disease." (PMID 32719677, 2020). "IL-33 expressing CAFs were reported at around 40% in colorectal cancer 24 and hepatocellular carcinoma 25 which was lower than the 71% in CAFs in CCA tissues found in this work." (PMID 33046978, 2020). "As has been shown in our repost from human colorectal cancer, IL-33-IR was predominantly detected in nuclear of squamous epithelial cells and stromal cells in both ESCC and control tissues." (PMID 30559604, 2018). "We analyzed IL-33 gene expression in human colorectal cancer (CRC) tissues and carried out gene enrichment analysis with TCGA Data Portal." (PMID 30119635, 2018). "IL-33 promoted growth and liver metastasis of colorectal cancer in mice by remodeling the tumor microenvironment and inducing angiogenesis." (PMID 29568370, 2018). "The soluble form of the IL-33 receptor (sST2), resisting IL-33-induced angiogenesis, is downregulated in metastatic cells compared with low-metastatic colorectal cancer cells." (PMID 30619376, 2018). "It is known that IBD patients have an increased risk for development of colitis-associated colorectal cancer (CAC), but the role of IL-33 in the development of colorectal cancer has yet to be fully examined." (PMID 28710436, 2017). "IL-33 expression was detected in epithelial cells in colorectal cancer specimens and in the ApcMin/+ mice." (PMID 28710436, 2017). "Interleukin-33 (IL-33) was recently shown to be involved in the inflammatory tumour microenvironment and the progression of colorectal cancer (CRC)." (PMID 27882929, 2016). "As expected, IL33 promoted liver metastasis in mice with colorectal cancer." (PMID 41214328, 2025). "The diminished IL-17A response in higher-grade tumors may reflect immune suppression or altered cytokine signaling in more advanced disease states, highlighting the interconnected roles of IL-8, IL-17A, and IL-33 in colorectal cancer." (PMID 40725273, 2025). "Considering the critical role of biomarkers in understanding the molecular biology of colorectal cancer, in the present study we examined the expression levels of IL-8, IL-17A, and IL-33 in relation to tumor grade and invasion, while also evaluating the correlations between these three interleukins." (PMID 40725273, 2025).
colorectal cancer (continued). "Likewise, IL-33 neutralisation also decreased the size and number of tumours in an experimental model of colorectal cancer." (PMID 38662248, 2024). "A correlation between IL33 and colorectal cancer progression has already been suggested." (PMID 38398137, 2024). "The anti-tumor function of IL-33 has been reported in myeloma and colorectal cancer models." (PMID 38816352, 2024). "Furthermore, inhibiting the IL-33/ST2 pathway in a mouse model of AOM/DSS-induced colorectal cancer can reduce the proliferation and migration of CD4+Foxp3+ST2+ Treg cells by downregulating integrins and chemokine receptor expression." (PMID 37686309, 2023). "Apart from its indirect effects, IL-33 also directly promotes colorectal cancer." (PMID 37686309, 2023). "In human colorectal cancer, the levels of both mRNA and protein of IL-33 were increased in tumor cell lines, biopsies as well as the systemic circulation of patients, while genetic deficiency in IL-33 decreased tumorigenesis in an intestinal tumor model using the ApcMin/+ mice." (PMID 34209038, 2021). "Moreover, high IL-33 (50 ng/ml) inhibited the growth and promoted apoptosis in colorectal cancer 36 and pancreatic cancer." (PMID 33046978, 2020). "In addition, the ILC2-activated cytokine IL-33 mediates host antitumor immunity, angiogenesis, and stromal remodeling in colorectal cancer pathogenesis and supports the effector functions of cytotoxic NK and CD8+ T cells." (PMID 31781671, 2019). "Similarly, neutralization of IL-33 inhibits the development of colorectal cancer in mice, as IL-33 promotes TREG cell accumulation." (PMID 30949175, 2019). "Thus, further studies should consider the contribution of IL-33 and IL-33-activated ILC2s to the pathogenesis of colorectal cancer." (PMID 31781671, 2019). "Abnormally high IL-33 expression was also found in human colorectal cancer (CRC) tissues." (PMID 30119635, 2018). "IL-33 facilitates proliferation of colorectal cancer dependent on COX2/PGE2." (PMID 30119635, 2018). "In a mouse colon cancer model using the MC38 cell line, it is shown that IL-33 level is significantly elevated in colorectal cancer liver metastasis and overexpression of the full-length IL-33 can promote tumor growth and increase liver metastasis incidence through myeloid cell recruitment." (PMID 29499051, 2018). "IL-33/ST2 pathway facilitated metastasis of human colorectal cancer." (PMID 29568370, 2018). "IL-33 is a pro-inflammatory cytokine with a role in colorectal cancer." (PMID 27882929, 2016). "Targeting IL33 could be a promising therapeutic approach for colorectal cancer liver metastases." (PMID 41214328, 2025). "Furthermore, IL33 may act as a promoter or inhibitor of colorectal cancer tumourigenesis depending on the specific cancer subtype." (PMID 38398137, 2024). "In eosinophils, IL-33-activated eosinophils can gain cytotoxic functions against tumor cells by directly killing tumor cells and by indirectly affecting immune regulatory pathways and are involved in restricting tumor growth in mouse models of colorectal cancer." (PMID 36291105, 2022). "Altogether, our findings demonstrate thecritical roles of interleukin 33 in promoting colorectal cancer development throughinducing tumor-infiltrating ST2L+ regulatory T cells, and inhibition ofinterleukin-33/ST2L signaling maybe a potential target for the prevention of colorectalcancer." (PMID 29950152, 2018). "It has been reported that ILC2s exert an essential role in the tumour-driven IL-33/ST2/IL-13 axis by promoting the migration and invasion of colorectal cancer cells, which are key factors promoting metastasis." (PMID 38662248, 2024). "IL-33, in contrast to earlier findings, has been observed to induce CCL2 expression in colorectal cancer cells, leading to the recruitment of macrophages and exertion of anti-tumor effects." (PMID 37686309, 2023).
colorectal cancer (continued). "sST2 acts as a “bait receptor” to competitively bind to IL-33 and block activation of the IL-33/ST2 signal which plays an important role in the development of colorectal cancer." (PMID 35406498, 2022). "In colorectal cancer (CRC), IL-33 levels were increased in cancer tissues, and IL-33 was shown to promote tumor growth and liver metastasis." (PMID 36291105, 2022). "The IL-33/ST2 axis is also involved in promoting tumor cell proliferation and colony formation in a COX2/PGE2-dependant fashion in colorectal cancer." (PMID 34209038, 2021). "Additionally, other cells that respond to IL-33 could contribute to the activation of EMT during colorectal cancer progress, as is the case of Tregs, which were described by Xiong and cols as promoters of EMT in a context of radiation-induced pulmonary fibrosis." (PMID 31281317, 2019). "IL-33: Interleukin-33, CRC: Colorectal cancer, n: number, T: tumor size, N: nodes." (PMID 38313904, 2024). "Furthermore, we validated NFE2L3 binding to the regulatory sequences of the IL33 and RAB27A loci in human colorectal carcinoma cells." (PMID 35091681, 2022).
dermatitis (56 papers, 2012 to 2025). An inflammatory process affecting the skin. "In this study, ILC2 depletion by RORα-deficient bone marrow transplantation markedly improved dermatitis, indicating that keratinocyte-derived IL-33 causes atopic inflammation through ILC2 activation." (PMID 35757747, 2022). "Dermatitis is typically associated with both skin-produced cytokines (e.g., IL-33, -17C, and TSLP), and a skewing of CD4+ T cells into T helper 2 (Th2) and their associated cytokines (e.g., IL-4,-5,-13,)." (PMID 33017398, 2020). "A simultaneous increase in the danger associated molecular pattern molecule IL-33 was observed, which has been associated with skin inflammation and itch response." (PMID 32065580, 2020). "A role for IL33 in the dermatitis in SHARPIN-deficient mice is supported by the attenuation of inflammation in Sharpincpdm mice in which IL1RAP was deleted." (PMID 24465642, 2014). "It was found that increased serum level of IL-33 may be caused by skin mechanical damage or barrier disruption, e.g., due to scratching, and exacerbate skin inflammation in AD." (PMID 41155460, 2025). "Additionally, blocking HDAC3 has been associated with reduced IL-33 expression and improved AD-like skin inflammation." (PMID 40612737, 2025). "IL-18, which independently causes AD-like skin inflammation and is associated with severity, and IL-33, an IL-1 cytokine family member that promotes Th2 inflammation and acts upstream in the cascade, were also elevated in the DNCB-induced Nc/Nga AD mouse model." (PMID 38139151, 2023). "Transgenic expression of IL-33 in murine skin causes spontaneous dermatitis to develop and, in humans, may modulate filaggrin expression and thus skin barrier function." (PMID 29378633, 2018). "The study suggests that IL-33 has a significant role in the development of AD and skin inflammation in the chronic phase of AD." (PMID 41155460, 2025). "However, it should also be noted that some other drugs, including epidermal growth factor receptor tyrosine kinase (EGFR-TK) inhibitors, may activate the IL-31/IL-33 axis as their adverse effect and initiate dermatitis, presumably by damaging keratinocytes and causing the release of IL-33." (PMID 41155460, 2025). "The results showed that CBG improved dermatitis severity score, epidermal thickness, and mast cell count and reduced inflammatory cytokines (Tslp, Il1b, Il4, Il6, Il13, Il17, Il18, Il22, and Il33) by qRT-PCR (p < 0.001)." (PMID 39851511, 2025). "In a mouse AD model, IL-33 overexpression in the skin of IL-33 Transgenic (Tg) mice spontaneously activated ILC2s and induced a pruritic dermatitis like AD, suggesting that IL-33 is involved in the onset of AD." (PMID 38590314, 2024). "In relevant studies on the pathogenesis of AD, the pathogenic role of keratinocyte derived cytokines such as thymic stromal lymphopoietin (TSLP), interleukin-33 (IL-33) and IL-25 in inducing skin inflammation has been emphasized." (PMID 38318507, 2023). "Epidermal barrier function largely relies on the SC barrier; perturbation of the SC barrier by tape stripping or acetone treatment has been shown to trigger the release of Th2 cytokines such as TSLP and IL-33, leading to subsequent skin inflammation." (PMID 35834333, 2022). "Tracking the migration of ILC2s in IL33tg-Kikume Green-Red mice revealed the migration of ILC2s from the skin to lymph nodes in the model of IL-33-induced dermatitis." (PMID 35757747, 2022). "Although innate immune responses play an important role in the MC903-induced AD-like dermatitis, in which TSLP and IL-33 produced by keratinocytes initiate the skin inflammation, adaptive immune cells are also required in the inflammation." (PMID 34868040, 2021). "A potential confounding issue is that mast cells can also respond to IL-33 through ST2 to elicit skin inflammation." (PMID 31940364, 2020).